IL2 (interleukin 2)
Diseases named in the same sentence as IL2 in open-access papers (continued):
Sharing a sentence is not in itself a finding about the gene and the disease.
tumor (continued). "To further confirm whether RdB/IL23/p35 mediates up-regulation of antitumor cytokines (IFN-γ and TNF-α) secreted by tumor-specific immune cells, we co-cultured splenocytes with irradiated B16-F10 or NIH3T3 for 3 days in the presence of recombinant human IL-2." (PMID 23844018, 2013). "In a single repetition, significant reductions in tumor growth were mediated by 1st gen dTc without IL2 (p=0.05) and 2nd gen dTc (p<0.001) with IL2." (PMID 23433424, 2013). "IL2-PE, a immunotoxin known to exert its cytotoxicity through binding to IL-2 receptor γ chain was not cytotoxic to IL-13Rα2 positive tumor cells confirming that IL-13-PE-mediated cytotoxicity is IL-13Rα2 specific." (PMID 23421960, 2013). "Jurkat cells, the parental tumor cell line from which J-Lat clones were derived, are IL-2-independent for their growth and survival, do not express the high-affinity IL-2 receptor, CD25, and express low levels of the IL-7 receptor alpha." (PMID 24385908, 2013). "When cytokine production was examined by flow cytometry, the IL-2 levels in the B16F10 cell line and at 7, 14 and 21 days of tumor growth were 45.72 pg/ml and 4.88, 7.37 and 13.55 pg/ml, respectively, and the IFN-γ levels were 1.05 pg/ml and 7.02, 3.75 and 0.95 pg/ml, respectively." (PMID 24179494, 2013). "Myeloid antigen-presenting cells and cytokines such as IL-2, TGF-β, IL-1, IL-23, and IL-6 may initiate Treg polarization into Th17-like cells in these tumor contexts (147–, 149)." (PMID 23986759, 2013). "Mart-126L- and/or GP100154/209/280-specific CD8+ T cells could be detected to similar levels in fresh (i.e. unexpanded) and IL-2, IL-15 and IL-21 aAPC expanded TIL samples, indicating that tumor antigen specificity was maintained after aAPC-mediated expansion." (PMID 23402380, 2013). "Adoptive CD8+ T cell therapy refers to an immunotherapy approach in which tumor-infiltrating lymphocytes (TILs) isolated from tumor specimen are activated and expanded in vitro to large quantities, using anti-CD3/CD28 antibodies and IL-2, and then transferred back to the cancer patients." (PMID 23785406, 2013). "In contrast to this, all the CD4+ T cell-deficient mice transferred with CTLs alone or CTLs together with Th(pMHC-I-/-), Th(CD40L-/-) or Th(IL-2-/-) cells failed to get protection, and had considerably increased tumor colonies of varying sizes in lungs." (PMID 23785406, 2013). "Anergy is a hyporesponsive state of T cells commonly encountered at tumor vicinity that is mediated by poor co-stimulation in absence of IL-2, a condition that upregulates various anergy related genes cbl-b, egr2, egr3, itch, GRAIL and DGK1α in T cells." (PMID 23785504, 2013). "The chief input of CD4+ T cells for anti-tumor effects operates through the direct help for the generation/augmentation of tumor-specific CTL responses and/or indirect help through secretion of various cytokines, such as IL-2 and IFN-γ." (PMID 24066030, 2013). "In particular, CTLA-4/B7 blocking in murine models results in increased IL-2 and interferon-gamma (IFN-γ) production by lymphocytes, increased expression of major histocompatibility complex (MHC) class I molecules, and markedly increased tumor killing." (PMID 23634660, 2013). "TIL were expanded from the tumor cell suspensions by stimulation with IL-2-, IL-15-, IL-21- or no cytokine-expressing aAPC, after which phenotype and function of the various cytokine-expanded TIL were analyzed." (PMID 23402380, 2013). "Interestingly, the IL-21 aAPC expanded CD8+ T cells demonstrated superior functional tumor recognition, with significantly higher IFNγ release levels than the CD8+ T cells expanded by IL-2 and IL-15 aAPC." (PMID 23402380, 2013). "Using tumor cells rather than IL-15 and IL-2 as stimulators also induced significant expression of CD86, but not CD80, on NK cells, both in vitro and in vivo." (PMID 24349559, 2013).
tumor (continued). "The model's equations illustrate the non-spatial dynamics between effector cells (E), tumour cells (T), IL-2 (I) and TGF-β (S) cytokines." (PMID 23734575, 2013). "However, a recent study identified that in established tumor models, CD27 signaling actually promoted tumor growth, with a reduction in Treg apoptosis and production of the Treg survival cytokine IL-2 by CD4+ effector T cells (TEff)." (PMID 23840967, 2013). "As a result, high levels of IL-2 and IFN-γ were found to inhibit tumor formation." (PMID 23710232, 2013). "When all data were pooled, both 1st and 2nd gen dTc had a significant impact on tumor growth in the absence of IL2 therapy." (PMID 23433424, 2013). "NK cell therapy without IL-2 administration significantly abrogated tumor progression, evidenced by reduced morbidity and mortality." (PMID 23326467, 2013). "For example, IL-2 is a potent stimulus for the activation of naïve T cells, but fosters at the same time activation-induced cell death of CD8+ effector T cells and induces Treg cells in tumor patients." (PMID 24312302, 2013). "In control subjects, CD107a is detectable at very low levels (<1%) on either resting and IL-2 activated NK cells, in the absence of co-culture with tumor target cells." (PMID 24302998, 2013). "In contrast, these same high avidity T cells produce multiple cytokines (IFNγ, IL-2, and TNFα) when transferred into tumor-bearing non-tolerant FVB/N mice." (PMID 22359647, 2012). "Stimulation with aAPC/mOKT3 did not expand Foxp3+ regulatory T cells, and expanded tumor infiltrating lymphocytes predominantly secreted Th1-type cytokines, interferon-γ and IL-2." (PMID 22279573, 2012). "After 72 h of incubation, we observed increased levels of IFN-γ, TNF-α, IL-10, IL-2, and TGF-β1 in the supernatant of RB tumor cell and PBMC cultures incubated with 1 μg/ml of EpCAM×CD3 antibody compared to an incubation with CD3 or EpCAM monoclonal antibodies alone." (PMID 22328825, 2012). "The MOSEC tumor cells treated with NKG2D-Fc-IL2 demonstrated significantly more luciferase activity in comparison to the MOSEC tumor cells treated with Con-Fc-IL2, NKG2D-Fc, or Con-Fc, or to the control (no treatment)." (PMID 22509395, 2012). "Spleen cells cultured in IL-2 (300 IU/mL) without irradiated tumor cells showed no cytotoxic activity (data no shown)." (PMID 22654951, 2012). "Inhibition of tumor growth was target-antigen-specific since growth of the C10 hybridoma was not affected by the HRS3-IL12-Fc-IL2 fusion protein." (PMID 23028547, 2012). "An additional administration of Interleukin-2 (IL-2) to RT also results in a better local tumor control and regression of the not irradiated tumor within the same mouse." (PMID 22848871, 2012). "In the mouse model, cetuximab treatment with or without IL-2 significantly inhibited intrathoracic tumor growth and prolonged their survival." (PMID 22922885, 2012). "To study the effects of pardaxin on tumor functions, we performed a real-time RT-PCR analysis of caspase-3, caspase-7, caspase-8, caspase-9, Bax, Bcl-2, STAT2, ATF3, STAT3, SOCS3, IL-2, cathelicidin, TNF-α, MyD88, NF-κB1, p65, IFN-β1, IFN-γ, IL-1β, IL-6, IL-7r, and IL-10." (PMID 23015777, 2012). "Our prototype vaccine was able to arrest progression of tumor growth when co-delivered in a specific regimen together with the costimulating multi-TLR agonist, Bacille Calmette Guerin (BCG) and interleukin-2, or with the Toll-Like receptor (TLR) 7/8 activator resiquimod." (PMID 24955288, 2012). "It is additionally quite conceivable that by the time patients are diagnosed and treated, that most tumor antigens actually represent memory T-cells which would not be dependent on IL-2 signaling to generate secondary immune responses." (PMID 22383993, 2012). "LAK cells, generated by culturing blood lymphocytes with high dose IL-2, are also able to lyse tumor cells in a non-MHC-restricted manner and have been applied in vivo for the treatment of various tumors." (PMID 23193418, 2012).
tumor (continued). "IL-2 and IFN-γ is a type of cytokine that plays an important role to inhibit tumor formation." (PMID 21941589, 2012). "Low dose entinostat, in combination with IL-2, did not have a direct cytotoxicity against tumor cells." (PMID 22303460, 2012). "Indeed, tumour-reactive CD4+ T helper 1 cells (Th1) produce several cytokines (such as IFN-fγ, TNF-α and IL-2) essential for the induction of cell-mediated immunity against tumours." (PMID 23284752, 2012). "IT administration of the IC was significantly more potent at tumor eradication than was IT administration of soluble IL2 (not shown), or of IT injection of a non-specific IC, KS-IL2 (not shown)." (PMID 24634778, 2012). "Here we demonstrate that our prototype vaccine is able to arrest progression of tumor growth when co-delivered in a specific regimen with the costimulatory-enhancing multi-TLR agonist, Bacille Calmette Guerin (BCG) adjuvant with interleukin-2, or with the TLR 7/8 activator resiquimod." (PMID 24955288, 2012). "Besides, IL-2 and IFN-γ production by human NKT cells has been shown to strongly activate NK cell cytotoxicity against tumor cell lines." (PMID 23028326, 2012). "The killer cells induced by cytokines IFN-γ and IL-2 and anti-CD3 monoclonal antibody (cytokine-induced killer, CIK) non-MHC-restrictive cytotoxic T lymphocytes, which kills tumor cells via recognition to a series of related ligands expressed in tumor surface." (PMID 22347323, 2011). "Among these, manipulation of BCG to secrete Th1 cytokines (e.g., IL-2, IL-18, IFN-γ, and IFN-α), alone or in combination with coexpression of bacterial or tumor antigens, represents one of the most attractive strategies for the development of improved vaccines." (PMID 21941579, 2011). "We modified the approach of TIL generation, using primary co-cultures of collagenase-digested tumor specimens rather than IL-2 outgrown microcultures derived from solid tumor fragments." (PMID 21827675, 2011). "LAK cells have no tumor specificity because they are induced in culture in response to IL-2 alone and not by tumor antigens." (PMID 21253521, 2010). "LAK cells are generally obtained by cultivating peripheral lymphocytes in the presence of IL2 (±lectins) yielding populations with different sets of T cells and NK cells with cytolytic properties not specifically directed against tumour cells." (PMID 20953324, 2010). "Given that the combination of IL-2+ IL-12+ IL-18 failed to enhance IL-17 production, alternative strategies will be required to promote this effector pathway within the tumor environment." (PMID 21203522, 2010). "Its expression is not sufficient for cytotoxic activity, since freshly isolated CD56+ γδ T cells and cells treated with IL-2 alone are not lytic for tumor cells." (PMID 20396597, 2010). "Moreover, some cytokines (IL-2, IL-21 and TNF) and heparin can act as anti-tumor mediators, released by mast cells, limiting tumor progression." (PMID 20569458, 2010). "The cytotoxic function of non-dissociated NK-tumor cell conjugates remained very low and did not increase when supplemented with IL-2 although they proliferated and secreted higher amounts of TNF-α and IFN-γ in the supernatants." (PMID 20360990, 2010). "For instance, high doses of IL-2 are administered to patients receiving antitumor T cells, but not always to tumor-bearing mice in these published reports." (PMID 21076522, 2010). "Additionally, a large amount of inflammatory cytokines, such as TNF-α, IL-2 and GM-CSF, are released by the activated CIK cells, which can directly inhibit tumor cells, or indirectly kill tumor cells by modulating the immune system." (PMID 20799994, 2010). "Inability of externally added IL2 to overcome tumor-PGE2 effect indicated that IL2 deprivation is not the primary cause of CD4+ cell death in our system." (PMID 19812686, 2009).
tumor (continued). "This is also the first observation that the administration of TKD/IL-2-activated PBMNC induces a sustained in vivo NK cell cytolytic response against the patient's own, Hsp70 membrane-positive tumor and the classical NK cell target K562 which persists for at least 2 months." (PMID 19549307, 2009). "In summary, we could demonstrate that 4 re-infusion cycles of ex vivo TKD/IL-2-activated PBMNC initiate and sustain an intrinsic NK cell-mediated cytolytic activity against autologous tumor and the NK cell target K562." (PMID 19549307, 2009). "A more immunogenic BCG also has implications for cancer as increasing host production of multiple cytokines with anti-tumor activity (i.e., IL-12p40, RANTES, IL21, and IL-2) has the potential to overcome some of the limitations of current BCG vaccines as cancer immunotherapy." (PMID 19436730, 2009). "In contrast, Th1 cytokines IL-2 and IL-7 are potent stimulators of T-cell cytotoxic activity and of memory CD8+ T cell survival, respectively, both of which are critical for effective tumor immunotherapy." (PMID 19956757, 2009). "One is specific immunotherapy which targets particular antigens in MPM tissue, and the other is a non-specific, but anti-tumor immunotherapy using such cytokines as interleukin 2 (IL-2), tumor necrosis factor (TNF), and interferon (INF)." (PMID 19830126, 2009). "The delivery of cytokines, either by single cytokines, for example, interleukin-2, interleukin-12, interferon-γ, interferon-α, or by a biologic mix of multiple cytokines, such as IRX-2, may result in tumor rejection and durable immune responses." (PMID 19680453, 2009). "Our data showed that IL-2 signal at priming stage in vitro drove development of CD8+ effector cells which produced greater quantities of IFNγ and Granzyme B when encountered the tumor in vivo." (PMID 19901991, 2009). "Our results support the hypothesis for a role of IL-2 in inhibiting blood vessels in MPM patients, suggesting a supplementary anti-cancer mechanism that is mediated by IL-2 in this type of tumour." (PMID 19935800, 2009). "Interestingly, tumours from mice vaccinated intratumorally with AJ-IL2/IL12 or Neuro-IL2/IL12 suggested a decrease of capillaries within the tumour compared to RPMI-treated controls, with most vasculature confined to the tumour periphery." (PMID 17595664, 2007). "Most importantly, a single injection of these cells, with no further supportive treatments with IL-2 resulted in significant tumor growth suppression in both subcutaneously grown tumor and lung tumor metastasis." (PMID 17592641, 2007). "None of the stage I patients died of recurrent disease, but two of 24 (8%) control patients and none of the IL-2-treated patients had a tumour recurrence during follow-up." (PMID 17031403, 2006). "Lymphocytes were freshly isolated from tumours, rested overnight and either used without further stimulation or expanded in IL-2 before testing their ability to migrate towards soluble vitronectin in chemotaxis assays." (PMID 17088900, 2006). "The mechanism by which these acute phase reactants interfere with IL-2-induced tumour regression is not defined." (PMID 16940978, 2006). "Mice treated with IL-21 + IL-2 after vaccination were the only animals that experienced no significant increase in tumor size." (PMID 16772043, 2006). "Seven patients who progressed during their vaccination protocol were not referred to receive IL-2: four because of rapidly progressing disease, one who refused and two patients who achieved CR following local irradiation of their tumour masses." (PMID 14970852, 2004). "Whereas cellular immune effector mechanisms are considered to be the most important mediators of IL-2 antitumour activity, IFN-α in addition is considered to exert antiproliferative and differentiation-inducing effects on the tumour cells." (PMID 14760375, 2004). "We found that IL-2 stimulated PBMC elicited a significant anti-tumor effect but not the combined effect of IL-2/IL-12 or IL-12 alone." (PMID 15485577, 2004).
tumor (continued). "However, interleukin-2 (IL-2)- and interferon-α (IFN-α)-based immunotherapy can induce durable tumour regression in 5–10% of patients with mRCC." (PMID 14760375, 2004). "Maximal tumour cell growth repression was found at lower doses of effector cells than in the absence of IL-2." (PMID 12671714, 2003). "In particular, we evaluated TCR ζ and ɛ chains, p56lck, Bcl-2 and Bax expression, FasL and Fas expression on the surface of TIL from surgically obtained tumour samples, and reassessed the same parameters, with the addition of perforin, after TIL were coincubated with IL-2." (PMID 12610520, 2003). "MD.45-HER/ζ or MD.45-mock CTL cultured in the absence of tumour targets produced less than 20 pg ml−1 IL-2." (PMID 12698199, 2003). "Utilising the C595 scFv, we generated an anti-MUC1-scFv-Fc-IL2 fusion protein that after binding to MUC1-positive tumour cells induces proliferation of peripheral blood T cells and mediates activation of resting NK cells to lysis of MUC1-positive tumour cells." (PMID 12966437, 2003). "In conclusion, there was neither a difference in survival time nor in tumour response rates when IL-2, applied according to the combined intravenous and subcutaneous schedule used for this study, was added to DTIC and IFN-α." (PMID 11308250, 2001). "Tamoxifen has been shown to potentiate in vivo anti-tumour activity of IL-2, and because of its non-toxic behaviour it was included in both groups." (PMID 9579838, 1998). "In summary, L-NAME had anti-tumour effects in vivo, reduced the severity of IL-2-induced capillary leakage in some organs and did not compromise anti-tumour efficacy of IL-2 therapy." (PMID 8546905, 1996). "Though encouraging, the clinical use of IL2 has so far been limited by toxicity, as well as by the heterogeneous and unpredictable responses and by the lack of specific anti-tumour effect." (PMID 1457368, 1992). "Results with bropirimine-activated or IL-2-activated NK cells emphasize that nonspecific activation is insufficient to eliminate all tumour subpopulations." (PMID 3224080, 1988). "Finally, IL-2 from CD4 + Th1 cells, in combination with IFN-γ, promotes cell proliferation and cytotoxic activity of CD8 + CTLs and NK cells working together to kill tumor cells." (PMID 41582199, 2026). "These fragments are maintained in IL-2-supplemented medium (1000–6000 IU/mL) under standardized conditions (37°C, 5% CO2) for 1–3 weeks, allowing spontaneous migration of lymphocytes from the tumor periphery into the culture medium, followed by collection of migratory TIL populations." (PMID 40458394, 2025). "Cytokines such as IL-2, interleukin-12 (IL-12), interferon-alpha (IFN-α), interferon-beta (IFN-β), and GM-CSF have demonstrated the ability to enhance the cytotoxic activity of both CD8+ T lymphocytes and NK cells while simultaneously inhibiting tumor cell proliferation." (PMID 40725830, 2025). "In addition, IL-2 treatment improves TME by promoting tumor infiltration by DCs and enhances sustained T-cell immunity against PDAC, whereas co-culture of IL-2 with PBMC significantly enhances the anti-tumor effects of DCs." (PMID 39958351, 2025). "Additionally, certain IL-2 therapies have inadvertently expanded regulatory T cells, which suppress anti-tumor immunity, particularly when lacking strategies to selectively target effector T cells." (PMID 39852848, 2025). "Similarly, we could see lower levels of primary IL-2 activated NK cell-mediated lysis of both OSCSCs and MP2 cells for sNK treated tumor cells when compared to primary activated NK cells." (PMID 40890122, 2025). "Till now, most research on the regulation of cytokine signaling by circRNAs in cancer is focused on tumor‐promoting cytokines; it is imperative to understand what role circRNAs play, if any, in regulating the effect of tumor suppressor cytokines such as IFN and IL‐2." (PMID 40356340, 2025).